ATR (ATR checkpoint kinase)
Description:
Serine/threonine protein kinase which activates checkpoint signaling upon genotoxic stresses such as ionizing radiation (IR), ultraviolet light (UV), or DNA replication stalling, thereby acting as a DNA damage sensor. Phosphorylates 'Ser-139' of histone variant H2AX at sites of DNA damage, thereby regulating DNA damage response mechanism. Required for FANCD2 ubiquitination. Critical for maintenance of fragile site stability and efficient regulation of centrosome duplication. Acts as a regulator of the S-G2 transition by restricting the activity of CDK1 during S-phase to prevent premature entry into G2. Acts as a regulator of the nuclear envelope integrity in response to DNA damage and stress. Acts as a mechanical stress sensor at the nuclear envelope: relocalizes to the nuclear envelope in response to mechanical stress and mediates a checkpoint via phosphorylation of CHEK1. Also promotes nuclear envelope rupture in response to DNA damage by mediating phosphorylation of LMNA at 'Ser-282', leading to lamin disassembly. Involved in the inflammatory response to genome instability and double-stranded DNA breaks: acts by localizing to micronuclei arising from genome instability and catalyzing phosphorylation of LMNA at 'Ser-395', priming LMNA for subsequent phosphorylation by CDK1 and micronuclei envelope rupture. The rupture of micronuclear envelope triggers the cGAS-STING pathway thereby activating the type I interferon response and innate immunity. Positively regulates the restart of stalled replication forks following activation by the KHDC3L-OOEP scaffold complex (By similarity).
Synonyms: FRP1; SCKL; SCKL1; MEC1; FCTCS
Tractability: Small molecule: a drug acting on it is in phase 2 or 3 trials; a high-quality ligand is known; it belongs to a druggable protein family. PROTAC: ubiquitination databases record sites on it; its protein half-life has been measured; a small molecule that binds it is known.
Target class: Enzyme; Atypical protein kinase group; Atypical protein kinase PIKK family; Protein Kinase; Kinase
Chemical probes: AZ20, AZD6738 (high quality), Berzosertib, CHEMBL2325703, Ceralasertib (high quality), PD082957, PD134287, PD134289, PD134291, VE-821, camonsertib, elimusertib
Gene: Protein-coding gene on chromosome 3 (142,449,007 to 142,578,781, reverse strand). Ensembl gene ENSG00000175054.
Subcellular location: Nucleus; Chromosome; Nucleus envelope
Subcellular location (Human Protein Atlas): Nucleoplasm; Golgi apparatus
Pathways (Reactome):
DNA Repair: Fanconi Anemia Pathway; HDR through Single Strand Annealing (SSA); Presynaptic phase of homologous DNA pairing and strand exchange; Processing of DNA double-strand break ends
Cell Cycle: Activation of ATR in response to replication stress; G2/M DNA damage checkpoint
Cellular responses to stimuli: Regulation of HSF1-mediated heat shock response
Disease: Impaired BRCA2 binding to RAD51
Reproduction: Meiotic synapsis
Gene Ontology:
Molecular function: histone H2AXS139 kinase activity; MutLalpha complex binding; MutSalpha complex binding; protein binding; protein kinase activity; protein serine kinase activity; protein serine/threonine kinase activity; kinase activity
Biological process: cellular response to gamma radiation; cellular response to UV; DNA damage checkpoint signaling; DNA damage response; double-strand break repair; establishment of RNA localization to telomere; mitotic G2/M transition checkpoint; negative regulation of DNA replication; nuclear membrane disassembly; positive regulation of telomerase catalytic core complex assembly; protein localization to chromosome, telomeric region; replicative senescence; response to mechanical stimulus; DNA repair; DNA replication; establishment of protein-containing complex localization to telomere; interstrand cross-link repair; positive regulation of telomere maintenance via telomerase; regulation of cellular response to heat; regulation of double-strand break repair; replication fork processing; chromatin remodeling; regulation of cellular response to stress; response to arsenic-containing substance; and 1 more
Cellular component: ATR-ATRIP complex; chromosome; nuclear envelope; nucleoplasm; nucleus; PML body; site of DNA damage; chromosome, telomeric region
Genetic constraint (gnomAD): Loss-of-function variants: 133 observed, 296.4 expected, observed/expected ratio (o/e) 0.45, 90% interval 0.39 to 0.52. The upper end of that interval is the gene's LOEUF score, 0.52, which puts it in group 2 of 6, group 1 being the genes least tolerant of losing a copy. Missense variants: 2,068 observed, 3,169.6 expected, observed/expected ratio (o/e) 0.65, 90% interval 0.63 to 0.68. Synonymous variants: 1,019 observed, 1,090.9 expected, observed/expected ratio (o/e) 0.93, 90% interval 0.89 to 0.98.
Cancer hallmarks: suppression of growth (promotes); genome instability and mutations (suppresses); change of cellular energetics (promotes); escaping programmed cell death (promotes)
Homologues: Orthologues: chimpanzee ATR (99% identical), macaque ATR (99% identical), dog ATR (95% identical), pig ATR (94% identical), rabbit ATR (93% identical), rat Atr (91% identical), mouse Atr (90% identical), guinea pig ATR (87% identical), tropical clawed frog atr (73% identical), zebrafish atr (65% identical), Drosophila melanogaster mei-41 (25% identical). Paralogues in human: PRKDC (20% identical), ATM (17% identical), MTOR (15% identical), TRRAP (14% identical), SMG1 (12% identical).
Diseases named in the same sentence as ATR in open-access papers:
ATR is named in the same sentence as 293 diseases in open-access papers, as found by Europe PMC text mining. Sharing a sentence is not in itself a finding about the gene and the disease. The quoted sentences say what the papers report.
breast cancer (135 papers, 2006 to 2026). A primary or metastatic malignant neoplasm involving the breast. "In breast cancer, high ATR expression levels were associated with high tumor stage, high tumor grade, a high mitotic index, polymorphisms, and lymphovascular invasion." (PMID 38669256, 2024). "ATR protein levels are down-regulated in breast cancer and high ATR protein levels are associated with higher tumor stage and lymph vascular invasion." (PMID 39334297, 2024). "Previous reports showed that rs13091637, which also located in the ATR intronic region and was in strong linkage disequilibrium with rs34660854 in Chinese population, was significantly associated with melanoma and breast cancer." (PMID 37468905, 2023). "In the framework of the EX2TRICAN project, exploring unresolved extreme cancer phenotypes, we applied exome sequencing on rare familial cases with male breast cancer, identifying a novel pathogenic variant of ATR (p.Leu1808*)." (PMID 36749285, 2023). "Several key initiators of the DNA damage response, including proteins, such as ataxia-telangiectasia mutated (ATM) and ATM- and Rad3-Related (ATR), are negatively regulated by ER in breast cancer." (PMID 37650943, 2023). "In a preclinical study, ARID1A deficiency was found to sensitize breast cancer cells to ATR inhibitor both in vivo and in vitro by causing topoisomerase 2A and cell-cycle defects." (PMID 36359297, 2022). "We performed the same analysis on the ATR residues mutated in endometrial, colorectal, or breast cancer and also found that only a few residues are on the surface." (PMID 33742106, 2021). "In the present study, we addressed the causes and consequences of ATR downregulation in breast stromal fibroblasts and the correlation between the ATR level and the clinical outcome of breast cancer patients." (PMID 32414408, 2020). "Engineered human breast tissue model was also used to show that ATR-deficient breast stromal fibroblasts enhance the growth of breast cancer cells." (PMID 32414408, 2020). "This indicates more proliferative and aggressive breast cancer cells while adjacent to ATR-deficient stromal fibroblasts." (PMID 32414408, 2020). "The procarcinogenic effects of ATR-deficient breast stromal fibroblasts were shown in vitro using direct coculturing in engineered human breast tissues composed of breast cancer cells and BSFs." (PMID 32414408, 2020). "Variants affecting the functionality of ATR have been related with high risk for colon and breast cancer." (PMID 32522261, 2020). "In a family that has colon, gastric and breast tumors, the variants p.Arg1436Gln in POLE and p.Pro2033Ser in ATR were identified in a breast cancer case and in her healthy brother of the index case." (PMID 32522261, 2020). "Pre-clinically, we observed that PTEN deficient breast cancer cells were sensitive to ATR inhibition and was associated with accumulation of DSBs, cell cycle arrest and induction of apoptosis." (PMID 29396668, 2018). "This shows that the presence of ATR-deficient breast stromal fibroblasts enhanced the EMT process in breast cancer cells in orthotopic tumor xenografts." (PMID 30410668, 2018). "In conclusion, we have demonstrated that ATR signaling adversely impact upon survival in PTEN-deficient breast cancers." (PMID 29396668, 2018). "ATR inhibition is synthetically lethal in PTEN-deficient TNBC cells implying a promising personalized therapy approach in breast cancers." (PMID 29396668, 2018).
breast cancer (continued). "This indicates that ATR-deficient breast stromal fibroblasts enhance the proliferation, migration and invasion abilities of breast cancer cells through paracrine secreted factors." (PMID 30410668, 2018). "In both cases ATR-deficient cells enhanced the growth of breast cancer cells, which was confirmed by showing the expression of high levels of Ki-67 and cyclin D1." (PMID 30410668, 2018). "We identified an association between ATR rs6805118 and breast cancer risk in the SBCS discovery set." (PMID 23844225, 2013). "Of these variants, the typed ATR SNP rs6805118 yielded the most significant signal for breast cancer risk, with p value of 7.6x10-5." (PMID 23844225, 2013). "The most significant associations for breast cancer risk in SBCS came from rs6805118 in ATR (p=7.6x10-5) and rs2155388 in CHEK1 (p=3.1x10-6), but neither remained significant after meta-analysis with other studies." (PMID 23844225, 2013). "The ATR synonymous rs1802904 SNP was found to be nominally significantly associated with breast cancer risk (p=0.0185) by means of the meta-analysis of the MEC European Americans, NHS postmenopausal women, SEARCH and SBCS data." (PMID 23844225, 2013). "Further analyses in other populations and larger cohorts will be required to define the possible association of ATR gene polymorphisms with breast cancer susceptibility." (PMID 17010193, 2006). "Association of ATR germline mutation with breast cancer susceptibility has been previously analyzed in Finnish 126 families, and no germline mutation was identified in this founder population." (PMID 17010193, 2006). "Additional studies in large cohorts and other populations will be needed to further evaluate if common and/or rare ATR sequence variants can be associated with a modest or intermediate breast cancer risk." (PMID 17010193, 2006). "The current study, performed in a French Canadian cohort, also being a founder population, was designed to assess the possible involvement of ATR germline deleterious mutations in breast cancer predisposition." (PMID 17010193, 2006). "The current study was designed to assess the possible involvement of ATR germline mutations in breast cancer susceptibility." (PMID 17010193, 2006). "Based on the major role of ATR in cellular response to DNA damage and its multiple interactions with several proteins such as BRCA1, ATR represents an attractive candidate gene to potentially explain a fraction of the remaining breast cancer susceptibility." (PMID 17010193, 2006). "ATR appears as a good candidate breast cancer susceptibility gene and the current study was designed to screen for ATR germline mutations potentially involved in breast cancer predisposition." (PMID 17010193, 2006). "However, ATR is frequently overexpressed in breast cancer, and its elevated expression levels are associated with advanced tumor stage and lymphovascular invasion, underscoring its potential as a therapeutic target." (PMID 40949156, 2025). "Such screening might broaden the treatment options for breast cancer patients, as these variants have been associated with enhanced effects of treatments such as ATR inhibitors and Gemcitabine in ovarian cancer." (PMID 37182128, 2023). "ATR has already been suspected as being a predisposing gene to breast cancer in women." (PMID 36749285, 2023). "Overall, these data provide some of the first evidence for divergences in the causal impact of ATM, CHK2, and ATR inactivation on the type of breast cancer a patient develops and on disease progression, i.e., metastatic potential and responsiveness to endocrine therapies." (PMID 37390209, 2023). "Moreover, an ongoing phase II trial is testing the combination of olaparib and cediranib or AZD6738 (ATR inhibitor) for the treatment of advanced or metastatic germline BRCA-mutated breast cancer (NCT04090567)." (PMID 38069409, 2023). "High ATR expression was found to be associated with late breast cancer stage and poor prognosis." (PMID 34484285, 2021).
breast cancer (continued). "In HR-proficient background, inactivation of POLQ increased cell death in ATR-deficient cells and sensitized breast cancer cells overexpressing POLQ to DNA damaging agents that cause replication stress (camptothecin and etoposide) or fork collapse (ATR inhibitors)." (PMID 34201502, 2021). "However, there are exceptions; for example, breast cancer has the highest number of mutated ATR residues (n = 122) despite a relatively modest mutation frequency (2%)." (PMID 33742106, 2021). "Indeed, ATR-deficient cells enhanced the growth of breast cancer cells, which was confirmed by showing the expression of high levels of Ki-67 and cyclin D1." (PMID 32414408, 2020). "Interestingly, combined PI3K and PARP inhibition have also provided more efficient responses in BRCA1-deficient breast cancer cells and dual ATR and BCR inhibition has also been proven to be synergistic in ATM-defective CLL cells." (PMID 31974435, 2020). "We provide the first clinical evidence that ATR signaling could have adverse impact on survival in PTEN-deficient breast cancers." (PMID 29396668, 2018). "Furthermore, the biological pathways ‘Role of BRCA1, BRCA2 and ATR in Cancer Susceptibility’ and ‘Breast Cancer’ were found in the top enriched terms for NA and SA regions with a p of 1.074×10−8 (2.09×10−10) and 2.804×10−5 (2.69×10−3), respectively." (PMID 30263132, 2018). "ATR signalling adversely impact survival in PTEN-deficient breast cancers." (PMID 29396668, 2018). "However, meta-analysis of published data revealed a weak association between the ATR SNP rs1802904 (minor allele frequency is 12%) and breast cancer risk, with a summary odds ratio (confidence interval) of 0.90 (0.83-0.98) [p=0.0185] for the minor allele." (PMID 23844225, 2013). "Based on the similar roles played by ATM and ATR as sensors of DNA damages, ATR may be considered a putative candidate gene that could possibly explain a fraction of the remaining familial breast cancer risk." (PMID 17010193, 2006). "Germline pathogenic variants in ATRIP and ATR are known to cause Seckel syndrome, a rare disorder characterized by growth impairment and neurodevelopmental abnormalities, and ATR variants have also been linked to several cancer types, including oropharyngeal, skin, cervical, and breast cancers." (PMID 41440239, 2025). "However, whether mutations in ATR/CHEK1 contribute to evolution of specific subtypes of breast cancer or to disease progression remains uncertain." (PMID 37390209, 2023). "Furthermore, we present clear indication that low levels of ATR in tumor cells as well as their adjacent stromal fibroblasts predict high risk of recurrence and poor survival post-neoadjuvant treatment of locally advanced breast cancer patients." (PMID 32414408, 2020). "In addition, the pre-clinical evidence presented here also suggests that ATR inhibition could be a promising synthetic lethality strategy in PTEN-deficient breast cancers." (PMID 29396668, 2018). "ATR targeting could be a promising synthetic lethality approach in PTEN-deficient breast cancers." (PMID 29396668, 2018). "In breast cancers with overexpression of low‐molecular‐weight cyclin E, ATR inhibition reduces cell viability by targeting the ATR–CHK1–RAD51 axis, underscoring the increased reliance of replication‐stress‐tolerant tumours on this pathway." (PMID 41537447, 2026). "Here, we demonstrate that AEP plays a dual role in the resistance of breast cancer (BC) patients to genotoxic stress through the regulation of ATR and PPP1R10 levels, key DNA repair effectors." (PMID 40012043, 2025). "This agent can be best combined with ATR inhibitors for breast cancers, which can improve the efficacy of adaptive T-cell therapy by preventing differentiation." (PMID 41278204, 2025).